IL10 (interleukin 10)
Diseases named in the same sentence as IL10 in open-access papers (continued):
Sharing a sentence is not in itself a finding about the gene and the disease.
dengue (continued). "In conclusion, several mechanisms have been previously proposed for ADE in dengue disease pathogenesis including promoting viral entry into FcR-bearing cells, the induction of IL-10 to inhibit the IFN-mediated anti-viral pathway, and the activation of DAK and Atg5-Atg12 to inhibit IFN production." (PMID 25329914, 2014). "Therefore, their data too appears to support that IL-10 appears to have a role in the pathogenesis of dengue." (PMID 23883139, 2013). "Serum IL-10 levels were significantly higher (p = 0.001) in patients with severe dengue (mean 291.6 ± SD 573.6, median 154.3, range 24.98 to 3271 pg/ml), when compared to those with non severe dengue (mean 156.6 ± SD 258.2, median 81.9, range 7.8 to 2681 pg/ml)." (PMID 23883139, 2013). "We found that serum IL-10 and IFNγ were significantly elevated in patients with severe dengue." (PMID 23883139, 2013). "Based on current knowledge of IL-10-mediated immune regulation during infection, researchers speculate an emerging role for IL-10 in clinical disease prognosis and dengue pathogenesis." (PMID 23800014, 2013). "For future strategies against DENV infection, manipulating IL-10 may be an effective antiviral treatment in addition to the development of a safe dengue vaccine." (PMID 23800014, 2013). "In these studies, IL-1ß, IFN-γ, IL-4, IL-6, IL-13, IL-7, GM-CSF (Granulocyte-macrophage colony-stimulating factor), MIF (macrophage migration inhibitory factor), IL-10 along with several other cytokines have been found to be elevated in patients with DHF when compared to dengue fever (DF)." (PMID 23883139, 2013). "Of the 17 patients in which the serum IL-10 levels rose, 5 had severe dengue." (PMID 23883139, 2013). "DHF patients showed high serum levels of IL-10, which may be involved in the pathogenesis of severe dengue disease." (PMID 22927911, 2012). "We found that severe dengue was associated with a reduction of total T cells and an elevation of IL-10 and TNFα, which was not, produced by NS3-specific T cells." (PMID 23209731, 2012). "Since IL-10 is known to play a role in dengue disease pathogenesis, it is possible that vitamin D could also contribute to disease pathogenesis through altered IL-10 response." (PMID 22559908, 2012). "We hypothesized that BAFF could be responsible for the observed plasmablast response in dengue patients since IL-10, which is highly up-regulated during acute dengue infection, can induce BAFF-expression." (PMID 22216280, 2011). "While IL-10 may contribute to the suppression of the immune system, leading to an inadequate antiviral response and an uncontrolled inflammatory reaction, which in turn contributes to the development of severe dengue." (PMID 38176525, 2024). "IL-10 is a critical cytokine in dengue infection and its levels are reported to be strongly increased in both DF and SDD patients." (PMID 39583156, 2024). "However, the immunosuppressive function of IL-10 could be a major determinant of its contribution to dengue pathogenesis." (PMID 28827898, 2017). "In contrast to other studies that showed correlation of increased IL-8 and IL-10 with dengue severity, we observed both cytokines to be down-regulated in dengue patients which may be due to low of number of actual severe dengue patients in this study." (PMID 24647042, 2014). "Therefore, inhibiting immunosuppression by targeting the IL-10 pathways identified in this study may help to prevent the progression of severe dengue diseases." (PMID 25412261, 2014). "With respect to a possible pathogenic role for aberrant IL-10 production in DHF/DSS patients, targeting the Syk/PKA/PI3K/PKB/GSK-3β/CREB signaling axis may represent a viable therapeutic strategy for combating the progression of severe dengue diseases." (PMID 25412261, 2014).
dengue (continued). "In order to determine if IL-10 could be suppressing DENV-specific T cell responses, we carried out ex vivo IFNγ ELISpots for NS3 and FEC in 10 of the patients with acute dengue and 4 healthy controls following blockade with anti-IL-10 and anti IL-10R antibodies." (PMID 24040431, 2013). "Targeting IL-10 regulation and signaling pharmacologically using neutralizing antibodies, antagonists, and inhibitors may represent a viable therapeutic strategy for combating the progression of severe dengue diseases." (PMID 23800014, 2013). "In a subsequent analysis comparing mild dengue with the combined DFWS/SD group, significantly higher exosomal levels of IL-1β, IL-5, IL-10, IL-12, IL-13, and TNF-α were observed in the DFWS/SD group (all p < 0.05)." (PMID 41993203, 2026). "This aligns with clinical observations of higher viremia, elevated IL-10 levels, and reduced IFN levels in patients with severe dengue." (PMID 40573398, 2025). "•Elevated IL-8, IL-10, IL-6, GM-CSF, MCP-1, IL-13, and IL-4 and decreased IL-12, MIP-1β on the third day after symptom onset is predictive of severe dengue." (PMID 38176525, 2024). "Recent studies have reported greater viral replication and IL-10, IL-6, and IL-1β levels in patients with a history of SDD than in individuals with a history of milder dengue disease." (PMID 39583156, 2024). "At the same time, there were a few non-specific correlations of the cytokines with the viral load and a significant positive correlation with IL-10 at 5 and 6 DPS, mainly the severe Dengue cases." (PMID 38176525, 2024). "Our findings reveal a distinct cytokine profile (elevated IL-8, IL-10, IL-6, GM-CSF, MCP-1, IL-13, and IL-4 and decreased IL-12, MIP-1β) on the third day after symptom onset is predictive of severe dengue in secondary dengue infection." (PMID 38176525, 2024). "Several studies have found that IL-6, IL-17A, IFN-α, IL-1β, IL-10, and TNF-α play different roles in dengue disease, but we didn't know which factor play key roles or even correlated with IL-37b and other factors." (PMID 37024713, 2023). "Several cytokines, including TNF-α, IL-6, IL-10 and IFN-γ, have been proposed as potential predictors of dengue severity." (PMID 36674524, 2023). "On evaluating the cytokine function of the TFH CD4+ T cells in DSV4 immunized mice, we found that dengue EDIII 1-4 peptide pool stimulation resulted in a significantly higher proportion of IL-21+ and IL-10+ TFH CD4+ T cells." (PMID 36926350, 2023). "More specifically, pro-inflammatory cytokines TNF-α, IL-1β, IL-6, and anti-inflammatory cytokine IL-10 have been shown to be elicited in DHF patients, and in dengue two-hit mouse models." (PMID 37298220, 2023). "CD4+ and CD8+ T cells from dengue-infected patients stimulated with envelope and NS3 dengue antigens produce multifunctional T cells secreting IFN-γ, TNF-α, and IL-10." (PMID 38003826, 2023). "Among them, a vast panel of increased cytokines and chemokines in severe dengue, such as IFN-γ, GM-CSF, IL-10, CCL4/MIP-1β, IL-1β, CXCL8/IL-8 TNF-α, CXCL10/IP-10, CCL2/MCP-1, and IL-18." (PMID 35631030, 2022). "Of the cytokines evaluated, IL-10 was significantly higher in patients with severe COVID-19 pneumonia and in those who developed dengue hemorrhagic fever (DHF) compared with DF, indicating IL-10 as a biomarker of an altered antiviral response potentially contributing to disease severity." (PMID 35631030, 2022). "An earlier report also demonstrated synthesis of TNF-α, IL-6, and IL-10 from circulating B cells, monocytes, and mDC in PBMC of pediatric dengue patients; culture supernatants from these purified B cells activated allogeneic T cells." (PMID 34335578, 2021). "The dengue patients with mucosal bleeding (n = 22) presented significantly increased plasma levels of IL-6 (median: 20 pg/mL; IQR: 11.4–38.8; p = 0.005) and IL-10 (median: 4.1 pg/mL; IQR: 2.7–11.8; p = 0.028) compared to those without mucosal bleeding." (PMID 34578370, 2021).
dengue (continued). "In our study, higher plasma levels of the proinflammatory cytokines TNF-α, IL-6 and IL-18, and the anti-inflammatory cytokine IL-10 and the chemokines CXCL8/IL-8, CCL2/MCP-1 and CXCL10/IP-10 were found in the dengue patients compared to the healthy controls." (PMID 34578370, 2021). "Another study showed that B cells isolated from pediatric dengue patients spontaneously secreted TNF-α, IL-6, and IL-10, and supernatants from cultures of purified B cells induced activation of allogeneic T cells." (PMID 34293057, 2021). "We also observed significantly greater numbers of dual-functional IL-10+TNF-α+ granulocytes and IFN-γ+TNF-α+CD56+CD3+ NKT cells in dengue patients than in febrile controls, although the percentages of the former were low." (PMID 34335578, 2021). "Many different chemokines and cytokines have been shown to be elevated in severe dengue such as IFN-γ, GM-CSF, IL-10, MIP-1β, IL-1β, IL-8 TNFα, IP-10, MCP-1, and IL-18." (PMID 33194836, 2020). "Early studies have shown that ADE of the dengue virus infection downregulates the production of IFN-β, IFN-γ, TNF-α and IL-12, and upregulates the production of IL-6 and IL-10." (PMID 32046249, 2020). "Interaction of platelets isolated from dengue patients with monocytes from healthy individuals lead to the synthesis and secretion of IL-1β, CXCL8, and IL-10 by the monocytes." (PMID 33102253, 2020). "NS1 was also shown to induce IL-10 production by monocytes and the persistence of NS1 antigenaemia in patients with acute dengue, correlated with the persistent high levels of IL-1042." (PMID 33199778, 2020). "This study reports the key inflammatory mediators IFN-γ, GM-CSF, IL-10, and MIP-1β as markers of disease severity in dengue patients." (PMID 30626045, 2019). "The next step was to quantify the serum levels of IL-1β, IL-6, IL-18, IL-10, TNF-α and CRP, as indicators of the inflammatory status in the dengue patients." (PMID 30901375, 2019). "Both sera interleukin 10 (IL-10) and alanine aminotransferase (ALT) levels were higher in those with severe dengue compared to those with mild dengue." (PMID 28536674, 2017). "Acute serum IL-6, IL-10 and TNF-α levels were measured in 22 dengue patients (12 DF and 10 DHF patients) either on enrollment (n = 19) or 1 day (n = 3) afterwards." (PMID 28393899, 2017). "Increased numbers of TNF-α-, IFN-γ-, IL-10- and TGF-β- expressing cells such as macrophages and lymphocytes were characterized in the tissues of dengue cases, when compared to controls." (PMID 28006034, 2016). "Inflammation mediators including IL-1α, IFN-γ, IL-10, IL-8, IP-10, MCP-1 and sVCAM-1 displayed significant differences on day 8-10 of illness between mild and severe dengue patients." (PMID 27301555, 2016). "Concerning the number of cells expressing TGF-β, IL-10 and RANTES, in dengue cases we noted increments of about 2.5-, 3- and 13-fold, respectively." (PMID 28006034, 2016). "Information on lymphocyte and platelet counts, levels of IL-10 and MIF, levels of AST and ALT, levels of gene expression and cell free DNA will aid in predicting severe dengue." (PMID 26462910, 2015). "However, these experiments do not rule out IL-10 causing T cell apoptosis in patients with acute dengue infection as we did find that serum IL-10 levels correlated well with T cell apoptosis in patients with acute dengue." (PMID 24040431, 2013). "IFN-α, IL-10, IL-12 IL-15, IP-10, MIG and MIP-1β were significantly increased or decreased in dengue patients compared to healthy controls if patients were classified according to the 2009 WHO classification." (PMID 23717702, 2013). "High levels of IL-10 and VEGF have been described in severe dengue, especially at the day of defervescence." (PMID 23717702, 2013). "Levels of IL-10, IL-15, VEGF, G-CSF and IP-10 were increased in ‘severe dengue’ cluster C in the cluster analysis." (PMID 23717702, 2013).
dengue (continued). "Serum IL-10 and MIF levels were determined in 65 patients (7 of them with severe dengue) in both the febrile phase and the critical phase." (PMID 23883139, 2013). "High IL-10 and TNF-α serum values were also found in patients with severe course of dengue hemorrhagic fever and Argentine hemorrhagic fever, which have similar clinical presentations to HFRS." (PMID 21605369, 2011). "Third, while we assessed a comprehensive set of clinical, laboratory, and virological factors, we did not analyze biomarkers such as IL-10, chymase, kynurenine, or transcriptomic signatures that have been identified as indicators for severe dengue." (PMID 41348908, 2025). "IL-10 and CXCL10 were previously shown to be markers of dengue severity and plasma leakage." (PMID 36595532, 2023). "Furthermore, an imbalance of IL-10 and IL-6, and SOCS1/3 has been observed in patients with severe dengue virus infection." (PMID 37376550, 2023). "As for dengue NS1, we also detected the production of TNF-α and IL-10 by mouse splenocytes." (PMID 36674524, 2023). "As in our previous studies, the dengue patients had high plasma levels of the cytokines TNF-α (p < 0.001), IL-6 (p = 0.005), IL-10 (p < 0.001) and, IL-18 (p = 0.001) and the chemokines CXCL8/IL-8 (p < 0.001), CCL2/MCP-1 (p < 0.001), CXCL10/IP-10 (p = 0.001) compared to healthy controls." (PMID 34578370, 2021). "Our first priority was to compare the levels of IL-1b, IL-2, IL-4, IL-6, IL-8, IL-10, IL-12p70, IL-17A, IL-33, CD14, CD54, CD62E, CD62L, CD62p, CD106, CD121b, CD154, CD178, GM-CSF, IFN-g, MIF, ST2 and TNF in plasma samples of dengue group, OF group and Healthy group." (PMID 33809042, 2021). "A study conducted in New Delhi, India, demonstrated a significant rise in serum IL-10 levels in severe dengue infection as compared to healthy controls and non-severe dengue fever." (PMID 32375246, 2020). "CD19+CD24hiCD38hi and CD19+CD27− naïve B cells from dengue patients did not produce IL-10 cytokine upon stimulation." (PMID 31736948, 2019). "In this study, the multiplex bead array reported for the first time literature in human patients infected with dengue virus revealed that the GM-CSF, IFN-γ, IL-10, IL-15, IL-8, MCP-1, IL-6, MIP-1β, and TNF-α levels were significantly raised in dengue subjects compared to healthy controls." (PMID 30626045, 2019). "In dengue patients the nine plasma cytokine levels were significantly elevated when compared to healthy controls: GM-CSF, IFN-γ, IL-10, 1L-15, IL-8, MCP-1, IL-6, MIP1β, and TNFα (p = 0.008, 0.0001, 0.0001, 0.0003, 0.0001, 0.001, 0.0003, 0.001 and 0.006 respectively) levels." (PMID 30626045, 2019). "CD19+CD24hiCD38hi and CD19+CD27− B cells from dengue patients were refractory to TLR stimulation in vitro, resulting in decreased B-cell-specific IL-10 and TNF-α cytokine production, which correlates to an increased expression of inhibitory FcγR in vivo in naïve B cells from DENV-infected patients." (PMID 31736948, 2019). "However, the most critical observation was that IFN-γ, GM-CSF, IL-10, and MIP-1β differentiated severe dengue patients from dengue fever cases in our cohort." (PMID 30626045, 2019). "Several candidates have been studied to explore severity predictors in dengue such as vascular endothelial growth factor (VEGF), tryptase and chymase, transforming growth factor-beta (TGF-b), and VEGF receptor-2, cytokines (IL-10, IFN-γ) and plasma IgE levels." (PMID 30871553, 2019). "To investigate the relationships among endothelial glycocalyx, cytokine levels and disease severity in dengue, we conducted a prospective longitudinal study to measure serum HA, HS, IL-6, IL-10 and TNF-α concentrations in adults diagnosed with dengue and other acute febrile illness." (PMID 28393899, 2017). "One study found that patients who developed severe dengue had significantly lower T cell counts when compared to non-severe dengue, whilst their serum IL-10 and IP-10 levels positively correlated with T cell apoptosis." (PMID 28569153, 2017).
dengue (continued). "Studies show that elevated levels of IL-6, IL-10, IFN-γ, MIF, and CCL-4 could be used as potential predictors of severe dengue." (PMID 27903271, 2016). "Although, our data do not show that IL-17 or IL-10, are in fact responsible for the liver injury in dengue, the findings suggest that it would now be important to investigate their role in more detail in acute dengue infection." (PMID 27391896, 2016). "The small difference in IL-10 levels in our study is unlikely to explain the imbalance in hospitalization for breakthrough dengue among children aged <9 years between the two groups." (PMID 27459266, 2016). "A paired comparison of these 15 cytokines (irrespective of the treatment group) showed that 12 (eotaxin, FGF-2, IFN-γ, IL-10, IL-1Ra, IL-1α, IL-8, IP-10, MCP-1, MDC, TNF-α and sCD40L) were differentially expressed between baseline and acute phase of dengue illness." (PMID 27459266, 2016). "In addition, due to reports of the elevation of IL-10 in DHF patients, IL-10 has been suggested as a biomarker of severe dengue." (PMID 27055163, 2016). "Sorting of monocytes from dengue patient peripheral blood mononuclear cells revealed that it is the CD14+ cells, but not the CD16+ or the T or B cells, that were infected with dengue virus and were major producers of IL-10." (PMID 26982706, 2016). "Several studies have shown that serum IL-10, IFNγ and MIF are elevated in patients in severe dengue (SD) and could be used as potential biomarkers." (PMID 23883139, 2013). "Using for example the 2009 WHO classification IL-10, IL-15, IP-10 and MIG were significantly elevated in dengue patients compared to healthy controls, but levels were not significantly elevated in severe compared to uncomplicated dengue." (PMID 23717702, 2013). "Other longitudinal studies have also shown that serum IL-10 levels increased during defervescence in dengue patients with warning signs, but IL-10 levels fell in those with no warning signs." (PMID 23883139, 2013). "Some have shown that MIF, IL-10, IL-6, MIP-1ß and IFNγ could be used as potential predictors of severe dengue." (PMID 23883139, 2013). "IL-10 blockade also did not have any effect on DENV-NS3 specific responses in healthy dengue seropositive volunteers." (PMID 24040431, 2013). "We did not observe significant production of TNFα, IL-10, IL-4, IL-13, IL-17 by dengue NS3-specific T cells, suggesting a different source for these cytokines in the serum." (PMID 23209731, 2012). "It is interesting to note that the temporal sequence of cytokine secretion is also similar between acute dengue and acute HIV infections, in that IFNα is made first, followed by the secretion of inflammatory cytokines, and lastly the anti-inflammatory cytokine IL-10." (PMID 21206915, 2010). "High expression of IL-6, IL-10, and IFN-α in DF patients was consistent with previous studies which showed that infection with dengue virus leads to elevated levels of these cytokines which are significantly increased in plasma of dengue patients." (PMID 37024713, 2023). "Based on the extensive literature on serum cytokines in dengue patients that implicates these soluble mediators in protection/severity, we chose to query TNF-α, IP-10, IL-6, and IL-10 from monocytes and granulocytes along with TNF-α, IP-10, IL-10, and IFN-γ from NK and NKT cell subsets." (PMID 34335578, 2021). "Although the exact source of IL-10 is not known in acute dengue, given that high levels are present at early illness, it could be produced from monocytes and other immune cells." (PMID 33199778, 2020). "Therefore, IL-10 and ALT can be taken as the biomarkers of sever dengue disease." (PMID 28536674, 2017). "However, when validating the use of serum IL-10 in a larger population of dengue patients, we found that serum IL-10 is unlikely to be useful as a biomarker because of its variability." (PMID 23883139, 2013).